ARG1 (arginase 1)
Diseases named in the same sentence as ARG1 in open-access papers (continued):
Sharing a sentence is not in itself a finding about the gene and the disease.
tumor (continued). "In return, microglia secrete tumor proliferation promoting factors including epidermal growth factor (EGF) and vascular endothelial growth factor (VEGF), TGF-β, arginase-1 (ARG1), and IL-10." (PMID 30319362, 2018). "We subsequently conducted immunohistochemical analyses on formalin-fixed tumor slices and recorded an increased presence of CD45+/ CD68+ cells having an elevated expression of Arg-1 and TGF-β1 in tumors from gemcitabine-treated mice, compared to those treated with vehicle only." (PMID 30097594, 2018). "The tumor-infiltrating macrophages in HSC-NOG-hIL-6 Tg mice expressed a high level of CD163, a marker of immunoregulatory myeloid cells, and produced immunosuppressive molecules such as arginase-1 (Arg-1), IL-10, and VEGF." (PMID 29456539, 2018). "After CM stimulation, the tumor educated macrophages (TEM) decreased the expression of M1 macrophage markers, such as IL-1b, IL-6 and increased the expression of M2 macrophage markers including Arg1 and CD163 compared with M0 macrophage." (PMID 30180849, 2018). "Although multiple metabolites were increased in tumor-bearing mice, knockdown of other metabolic enzymes, namely arginase 1 and lactate dehydrogenases A and B, did not affect tumor burden." (PMID 29920191, 2018). "Tumour-derived mMDSCs showed higher levels of T-cell suppression in vitro that may be due to higher levels of nitric oxide synthase (NOS2) and arginase 1 (ARG1)." (PMID 28382931, 2017). "Combination of anti-CTLA-4 with selumetinib negated this up-regulation of Cox-2 and Arg1, reduced the frequency of CD11+ Ly6G+ myeloid cells, and led to the accumulation of differentiating monocytes at the Ly6C+ MHC+ intermediate state in the tumor." (PMID 28807001, 2017). "As the quantity and activity of TAMs could be explained by the expression of Arg1, Fizz1, Msr2, CCL3, CCL22, and so the mRNA levels of these factors in tumor tissues were detected." (PMID 29137420, 2017). "Therefore, we investigated the expression of Arg1, Fizz, Msr2, CCL3, CCL22 mRNA in tumor cells using RT-qPCR." (PMID 29137420, 2017). "The arginase 1 inhibitor nor-NOHA and the ODC inhibitor α-difluoromethylornithine (DFMO) downregulate arginase 1 expression in tumor-associated MDSC and restore T cell antitumor immunity." (PMID 28223985, 2017). "The differences observed between these two tumor models regarding Arg1 and MMT9 expression in MDSCs illustrate that different model may utilize different mediators in regulating tumor angiogenesis and immune suppression." (PMID 29070836, 2017). "The TAM and those factors are important parts of the tumor microenvironment, regulating cancer development, which is called the M2 phenotype of macrophage (usually expressing high levels of IL-10, VEGF and Arg-1; whereas expressing low levels of IL-12, IL-23 and iNOS)." (PMID 27107415, 2016). "In contrast to MDSCs, TAM upregulate the expression of either Arg-1 or iNOS, depending on the nature of the tumor microenvironment, but not of both proteins." (PMID 27191744, 2016). "In contrast to MPs, CD11b+/CD45low cells (primarily MG) did not express Arg1 initially, but eventually with tumor growth, most MG became Arg1+." (PMID 27936099, 2016). "Similar to WT mice, tumor MG in control animals that had undergone BM transplantation without GCV therapy expressed Arg1 within 1 week of tumor implantation and the proportion of Arg1+ MG increased with tumor growth." (PMID 27936099, 2016).
tumor (continued). "This IHC result was validated by immunoblotting analysis of tumor bearing glands, which showed abundant levels of Arg1 protein in IL4-AC2M2 tumors, but no detectable Arg1 in EV-AC2M2 tumors or normal mammary glands." (PMID 27563494, 2015). "No inhibition in tumor growth was observed when similar experiments, in which arg-1 was inhibited, were performed in mice lacking functional T and B cells." (PMID 25869209, 2015). "Higher levels of ARG1, iNOS, S100A8 and S100A9 in CD11b+Gr-1 + cells from Lewis- and B16- tumor bearing mice could be detected as compared to the counterparts from tumor-free mice." (PMID 26285119, 2015). "Next we found that tumor associated macrophages (TAMs) in progressive MCA-205-OVA tumors, but not MCA-205-E1A-OVA tumors that expressed high levels of arginase-1, which is known to have local immunosuppressive activities." (PMID 24614600, 2014). "Importantly, subcutaneous tumor lysates also demonstrated evidence of DMXAA-mediated repolarization, with diminished Arg-1 staining being evident as early as 6 hours post-DMXAA exposure." (PMID 24940883, 2014). "Interestingly, iNOS enzyme is expressed by M1-like macrophages and can be co-expressed with arginase-1 (ARG1) in MDSCs, resulting in l-Arg reduced availability and production of reactive nitrogen species (RNS) in tumor microenvironment." (PMID 24605112, 2014). "To determine whether the Tie2+ myeloid cells present in the tumor/normal brain edge upon anti-VEGF therapy are an M2 polarized population, we performed double immunofluorescence staining with Tie2 and Arg1." (PMID 24809734, 2014). "Finally, compared to MDSCs from B16 Neo-tumor-bearing mice, MDSCs from B16 MUC1 mice expressed significantly higher levels of iNOS and Arg-1." (PMID 24605110, 2014). "Definitive studies examining the role of arginase-1 production by TAMs and anti-tumor immunity are currently hampered by a relative lack of arginase-1 specific reagents." (PMID 24614600, 2014). "Tg-mediated ER stress enhanced the immunosuppressive capacity of tumor-infiltrating MDSCs by increasing expression of ARG1, iNOS, and NOX2, although splenic MDSCs were not affected." (PMID 25514597, 2014). "M2 macrophages may enhance tumour progression by releasing growth factors and products of the arginase-1/IDO pathway and by promoting tumour angiogenesis." (PMID 24093459, 2013). "Taken together, anti-tumor reactive T cells in CML may be controlled by multiple immune escape strategies including recruitment of MDSCs, expression of Arg1, PD-L1, PD-1, and sCD25." (PMID 23383287, 2013). "The authors suggested that up-regulated expression of arginase- 1 was associated with HCV infected liver, and to a lesser extent in tumor, but not in uninfected liver." (PMID 23111165, 2012). "Arginase activity was absent in cultured PANC02 (results not shown) and arginase 1 protein was never detected in tumor cells in vivo by immunostaining." (PMID 20856806, 2010). "Last, ARG1 was reported to promote HCC growth and metastasis by enhancing tumor cell epithelial-mesenchymal transition, whereas ectopic expression of ARG1 in a Tsc1/Pten DKO model suppressed HCC development by consuming arginine, and limiting arginine led to tumor cell growth arrest and apoptosis." (PMID 41512056, 2026). "The first phase I clinical trial of ARG1 inhibition in combination with anti-PD-1 demonstrated only limited anti-tumor activity when studied in numerous solid tumors including non-small-cell lung cancer, gastric cancer, renal cell cancer, melanoma, and urothelial carcinoma." (PMID 40507361, 2025). "The abundant presence of Arg1+ cells in the metastases of PcPAMP-vaccinated animals may provide further reasons to explain why we did not see a reduction in tumor metastases in our model." (PMID 40573917, 2025).
tumor (continued). "Although this blocking effect did not affect Arg1 expression in TMZ-resistant GBM tumor, blocking IL-19 still can downregulate the expression of STAT3-associated immunosuppressive genes (CD274 and S100A4) in both TMZ-sensitive and TMZ-resistant GBM tumor." (PMID 40057744, 2025). "In the tumor microenvironment, immunosuppressive myeloid cells upregulate amino acid-metabolizing enzymes, such as Arginase 1 (Arg1) and Indoleamine 2,3-dioxygenase 1 (IDO1), to deplete arginine and tryptophan—amino acids essential for T cell activation and function—thus promoting tumor progression." (PMID 39905317, 2025). "However, we only detected positivity for Arg1, suggesting macrophages in these models are immunosuppressive regardless of tumor GSR/TXNRD1 status." (PMID 40334547, 2025). "Within the tumor microenvironment, M2 cytokines, including IL-4, IL-13, and IL-10, are present, and TAMs in various cancer models exhibit an M2 activation profile characterized by increased expression of CD163, MRC-1, C-type lectins, IL-10, and Arg-1, as well as reduced production of IL-12." (PMID 40544275, 2025). "Although TAMs secreting arginase-1 are recognized to induce tumor immunosuppression in a wide variety of settings, it is not known whether TAM-T-cell interactions drive resistance to anti-PD1 plus chemotherapy in patients with CCA." (PMID 39969434, 2025). "However, this blocking IL-19 did not affect Arg1 expression in M2-like macrophage subset (MC04) in TMZ-resistant GBM tumor (data not shown)." (PMID 40057744, 2025). "Our mechanistic study revealed that TBC1D1-mediated inhibition of CTL function could be attributed to the upregulation of various immune checkpoint molecules, including ARG1, CD68, PDCD1, CD274, TGFB1, and CTLA4, collectively impeding the anti-tumor immune response." (PMID 38529286, 2024). "We further revealed that Arg-1 (P < 0.001), NOX-2 (P < 0.05), TGF-β (P < 0.05), and PD-L1 (P < 0.05) were significantly higher from Lect2−/− EOC than Lect2+/+ EOC, supporting their potential for inhibiting the tumor-infiltrating lymphocytes and silencing the immune response." (PMID 38177412, 2024). "Besides, AIM2 overexpression also could downregulate expression of M2 markers (Arg‐1 and YM1) in the tumor tissues." (PMID 39222064, 2024). "Moreover, in STS, both ARG1 and ARG2 gene expression have been identified in tumor samples, suggesting an immunosuppressive TME that may impede an effective immune response." (PMID 39502689, 2024). "Importantly, in vitro antibody-mediated neutralisation of ILC2-derived IL-4 and IL-13 reduced tumour MDSC Arg1 levels, and similarly genetic deletion of IL-13 in mice with CRC decreased Arg1+ MDSCs, increased IFNγ production by Th1 cells and CD8+ T cells, and significantly reduced tumour burden." (PMID 38464388, 2024). "However, these are not the sole mechanisms through which ARG1 promotes tumor growth, as its activity can also adversely affect the activation and function of tumor-infiltrating immune cells." (PMID 39211039, 2024). "These facts led the authors to posit that arginine and polyamine pools are decoupled in liver tumours; the additional observation that driving ARG1/AGMAT expression did not affect tumour polyamine levels argues against polyamines representing a significant arginine sink in this context." (PMID 39871876, 2024). "Arginase-1 (Arg-1) staining was more intense in MM tissue from chrysotile-induced MMs than in crocidolite-induced MMs, whereas iNOS staining was virtually absent in both tumor types and was mainly restricted to granulomatous lesions." (PMID 38592450, 2024). "Moreover, tumor-derived succinate triggers the reprogramming of peritoneal macrophages and enhances their migration via the succinate receptor 1 (SUCNR1)/PI3K/HIF-1α signaling pathway, ultimately increasing Arg1 expression and promoting arginine metabolism." (PMID 38185636, 2024).
tumor (continued). "Similarly, Lnc57Rik can not only bind with the C/EBPβ isoform LAP to activate C/EBPβ but also with the WDR5 that enables the enrichment of H3K4 on the promoter regions of Arg-1, NOS2, NOX2, and COX2, eventually resulting in their transcriptional activation in tumor." (PMID 37637063, 2023). "Since we found no immune cells with elevated ARG1 expression in the bone marrow or blood, we hypothesize that ARG1 expression was induced by local factors after tumour infiltration." (PMID 37980483, 2023). "Furthermore, phosphodiesterase-5 (PDE5) inhibitors such as sildenafil, tadalafil, and vardenafil can reduce the levels of ARG1 and iNOS, thereby reversing MDSC-mediated immune suppression, reducing inflammation in the TME, and reactivating anti-tumor T cells and NK cells." (PMID 37711747, 2023). "However, Arg-1 expression levels in the tumor parenchyma, but not stroma, were significantly different for recurrent and non-recurrent patients (p = 0.035)." (PMID 38001706, 2023). "Likewise, expression of ARG1 and ARG2 enzymes in both cancer and immunosuppressive cells leads to the depletion of another important amino acid, L-arginine, from the TME, suppressing T cell–mediated anti-tumor immunity." (PMID 36175673, 2023). "In addition, this study also demonstrated that low expression of SHP-2 further stimulated IL-4-induced M2 macrophages to produce IL-10 and Arginase-1, which in turn further aggravated macrophage M2 polarization and ultimately promoted CRC tumor invasion and metastasis." (PMID 36776333, 2023). "However, recent studies revealed Arg2, an isoform of Arg1 which functions in the mitochondria, is expressed in T cells and serves as a regulator of CD8+ T cell activation, anti-tumor cytotoxicity, and memory formation, independently of extracellular arginine concentration." (PMID 37277776, 2023). "This, however, could not be confirmed with the TCGA cohort, where gene expression levels of Arg-1 in the tumor had no impact on the overall survival of HNSCC patients." (PMID 38001706, 2023). "We further showed that co-culturing of BMDMs with PE tumor cells potently increased expression of inducible nitric oxide synthase (iNOS) and programmed death-ligand 1 (PD-L1) in macrophages, while arginase 1 and TGF-β were not significantly altered in macrophages." (PMID 36817465, 2023). "In addition, the loss of hepatic- and host-specific autophagy results in the release of the arginine-degrading enzyme arginase 1 (ARG1) into the bloodstream, resulting in a decrease in circulating arginine levels and rendering the primary tumor unable to sustain growth." (PMID 38067169, 2023). "However, prior to this work, a functional role of Arg1 in pancreatic TAMs and tumor immunity had not been evaluated." (PMID 36727849, 2023). "In the advanced stage of tumor progression and metastasis, TAMs usually favor the M2 phenotype, which is characterized by low expression of iNOS and IL-12, and high expression of CD206, Arg-1 and IL-10, promoting tissue repair and angiogenesis in favor of tumor progression." (PMID 37127625, 2023). "Tumor-derived lactate is taken up by GAMs through their monocarboxylate transporters (MCT1, MCT2 and MCT4), leading to the transcription of the vascular endothelial growth factor (VEGF) and the l-arginine- metabolizing enzyme arginase-1 (ARG1) genes inhibiting T-cell activation and proliferation." (PMID 35654889, 2023). "The immunosuppressive phenotype, exhibited by neutrophils after the tumor’s microenvironmental signals, is observed in biopsies of patients with HNSCC and inhibits tumoricidal functions of natural killer cells by secreting transforming growth factor beta (TGF-β), nitric oxide, and arginase-1." (PMID 37631922, 2023).
tumor (continued). "Moreover, PepO significantly switched TAM to the tumoricidal M1 macrophage as reflected by a reduction in the expression of M2 markers Arg-1, CD206, Fizz-1, Ym1 and IL-10 while increasing the expression of M1 markers iNOS, IL-12a and IL-1β and promoted apoptosis of the tumor cells." (PMID 37925462, 2023). "Similarly, IHC of the tumor likely underestimates true Arg-1 levels, because it does not account for the active exosome release, which is presumably enhanced in metastasizing, aggressive tumors." (PMID 38001706, 2023). "Although the immunosuppressive role of ARG1 is well established, its role as a marker of pro-metastatic immune cells, with its differential gene or protein expression in metastatic vs non-metastatic tumours, has not been extensively studied." (PMID 37980483, 2023). "Because IL-6 is a crucial regulator of MDSC activity and proliferation, leading to tumor cell survival, coupled with upregulated IL-6 in the serum of naïve CB2−/− females, we assessed the mRNA expression of IL-6 in the TME along with arginase-1 (Arg1), a functional marker of MDSCs." (PMID 36835468, 2023). "Furthermore, our data showed that CN133 in combination with anti-PD-1 improved efficacy significantly which was achieved in the subcutaneous murine PCa models by decreasing tumor-infiltrating PMN-MDSCs and their expression of functional molecules Arg-1 and iNOS." (PMID 37880708, 2023). "Moreover, arginine depletion in the TME promotes the accumulation of CD11b+Gr1+ MDSCs that suppress antitumor functions of T cells, and pharmacological inhibition of arg-1 suppresses the activity of G-MDSCs, restoring the production of IFN-γ and granzyme B by T cells and reducing tumor growth." (PMID 36713558, 2022). "Furthermore, lysates generated from adjacent but noncancerous lung tissue from PL mice did not induce Arg1 transcript production, suggesting that the operative factor was tumor specific." (PMID 36377658, 2022). "Although increased expression of COX-2 in human tumor tissue is followed by higher PGE2 production resulting in ARG1 induction in MDSCs,39 the lack of stimulation of ARG1 expression in our setting could be a characteristic of MDSCs in rats." (PMID 36184742, 2022). "Similarly, iWAT of C26 tumor-bearing animals exhibited higher expression of Arg1 (6.6-fold), Il-10 (2.4-fold), and Tgfß3 (1.8-fold) but not of Tgfß1 and -2 and iNos mRNA levels compared with control mice." (PMID 35210363, 2022). "Finally, BCG lysate also significantly enhanced the frequency of tumor-associated MΦ (TAM) and increased the proportion of iNOS+ M1 MΦ, while the proportion of Arg1+ M2 MΦ was not significantly altered." (PMID 35732347, 2022). "Not surprisingly, TANs from both tumor models possessed the largest population of ARG1+ cells." (PMID 36377658, 2022). "Indeed, adoptive transfer of Arg1+ but not Arg1- lung macrophages to Il9r−/− mice promotes tumor growth." (PMID 35778404, 2022). "By migrating to the tumor, MDSC elevates Arg1 and iNOS, downregulating ROS production, upregulating PD-L1 on MDSC surface, and producing CCL4 and CCL5 chemokines to attract T-regs, strongly suppressing the activity of CTLs and NK cells in the tumor microenvironment." (PMID 35214123, 2022). "In TME, in addition to tumor cells themselves escaping immune system attack through metabolic reprogramming evolution, many immunosuppressive cells can also express many extracellular enzymes, such as IDO, CD73, ARG1, etc., depleting nutrients to promote tumor progression." (PMID 35444235, 2022). "However, none of the previously reported ARG1-inducing cytokines were observed on the array or shown to be differentially presented in the tumor and adjacent lung." (PMID 36377658, 2022). "Single neither Arg-1 inhibitor nor anti-PD-1 antibody achieved obvious tumor growth inhibition." (PMID 35316682, 2022).